UBE2N (ubiquitin conjugating enzyme E2 N)
Description:
The UBE2V1-UBE2N and UBE2V2-UBE2N heterodimers catalyze the synthesis of non-canonical 'Lys-63'-linked polyubiquitin chains. This type of polyubiquitination does not lead to protein degradation by the proteasome. Mediates transcriptional activation of target genes. Plays a role in the control of progress through the cell cycle and differentiation. Plays a role in the error-free DNA repair pathway and contributes to the survival of cells after DNA damage. Acts together with the E3 ligases, HLTF and SHPRH, in the 'Lys-63'-linked poly-ubiquitination of PCNA upon genotoxic stress, which is required for DNA repair. Appears to act together with E3 ligase RNF5 in the 'Lys-63'-linked polyubiquitination of JKAMP thereby regulating JKAMP function by decreasing its association with components of the proteasome and ERAD. Promotes TRIM5 capsid-specific restriction activity and the UBE2V1-UBE2N heterodimer acts in concert with TRIM5 to generate 'Lys-63'-linked polyubiquitin chains which activate the MAP3K7/TAK1 complex which in turn results in the induction and expression of NF-kappa-B and MAPK-responsive inflammatory genes. Together with RNF135 and UB2V1, catalyzes the viral RNA-dependent 'Lys-63'-linked polyubiquitination of RIGI to activate the downstream signaling pathway that leads to interferon beta production. UBE2V1-UBE2N together with TRAF3IP2 E3 ubiquitin ligase mediate 'Lys-63'-linked polyubiquitination of TRAF6, a component of IL17A-mediated signaling pathway.
Synonyms: UbcH-ben; UBC13; MGC8489; HEL-S-71; UBCHBEN; UBCHBEN; UBC13; UbcH13
Tractability: Small molecule: a structure with a bound ligand is known; it belongs to a druggable protein family. PROTAC: UniProt records ubiquitination sites on it; ubiquitination databases record sites on it; its protein half-life has been measured; a small molecule that binds it is known.
Target class: Enzyme; Aminoacyltransferase
Chemical probes: ML307
Gene: Protein-coding gene on chromosome 12 (93,405,673 to 93,442,258, reverse strand). Ensembl gene ENSG00000177889.
Subcellular location: Nucleus; Cytoplasm
Subcellular location (Human Protein Atlas): Nucleoplasm; Nucleoli fibrillar center
Pathways (Reactome):
Immune System: Antigen processing: Ubiquitination & Proteasome degradation; CLEC7A (Dectin-1) signaling; Downstream TCR signaling; FCERI mediated NF-kB activation; IKK complex recruitment mediated by RIP1; IRAK1 recruits IKK complex; IRAK1 recruits IKK complex upon TLR7/8 or 9 stimulation; ISG15 antiviral mechanism; Interleukin-1 signaling; JNK (c-Jun kinases) phosphorylation and activation mediated by activated human TAK1; NOD1/2 Signaling Pathway; TAK1-dependent IKK and NF-kappa-B activation; TICAM1, RIP1-mediated IKK complex recruitment; TRAF6 mediated IRF7 activation in TLR7/8 or 9 signaling; activated TAK1 mediates p38 MAPK activation
DNA Repair: Formation of Incision Complex in GG-NER; Nonhomologous End-Joining (NHEJ); Processing of DNA double-strand break ends; Recruitment and ATM-mediated phosphorylation of repair and signaling proteins at DNA double strand breaks
Autophagy: Aggrephagy; PINK1-PRKN Mediated Mitophagy
Cell Cycle: G2/M DNA damage checkpoint
Disease: SARS-CoV-2 activates/modulates innate and adaptive immune responses
Metabolism of proteins: E3 ubiquitin ligases ubiquitinate target proteins
Gene Ontology:
Molecular function: protein binding; RNA binding; ubiquitin binding; ubiquitin conjugating enzyme activity; ubiquitin protein ligase binding; ubiquitin-protein transferase activator activity; ubiquitin-protein transferase activity
Biological process: antiviral innate immune response; DNA damage tolerance; DNA double-strand break processing; double-strand break repair via homologous recombination; negative regulation of TORC1 signaling; positive regulation of canonical NF-kappaB signal transduction; positive regulation of DNA repair; positive regulation of double-strand break repair; positive regulation of intracellular signal transduction; positive regulation of protein K63-linked ubiquitination; proteasome-mediated ubiquitin-dependent protein catabolic process; protein K63-linked ubiquitination; protein monoubiquitination; protein polyubiquitination; T cell receptor signaling pathway; protein ubiquitination; regulation of DNA repair
Cellular component: cytoplasm; cytosol; extracellular exosome; fibrillar center; nucleoplasm; nucleus; protein-containing complex; UBC13-MMS2 complex; ubiquitin conjugating enzyme complex; ubiquitin ligase complex
Genetic constraint (gnomAD): Loss-of-function variants: 0 observed, 15.56 expected, observed/expected ratio (o/e) 0, 90% interval 0 to 0.19. The upper end of that interval is the gene's LOEUF score, 0.19, which puts it in group 1 of 6, group 1 being the genes least tolerant of losing a copy. Missense variants: 56 observed, 172.95 expected, observed/expected ratio (o/e) 0.32, 90% interval 0.26 to 0.41. Synonymous variants: 62 observed, 64.63 expected, observed/expected ratio (o/e) 0.96, 90% interval 0.78 to 1.18.
Homologues: Orthologues: chimpanzee UBE2N (100% identical), macaque UBE2N (100% identical), mouse Ube2n (100% identical), rabbit UBE2N (100% identical), zebrafish ube2na (97% identical), zebrafish ube2nb (96% identical), tropical clawed frog ube2n (89% identical), pig UBE2N (88% identical), Caenorhabditis elegans ubc-13 (86% identical), Drosophila melanogaster ben (80% identical), Drosophila melanogaster CG3473 (78% identical). Paralogues in human: UBE2NL (91% identical), UBE2K (47% identical), UBE2T (44% identical), UBE2A (41% identical), UBE2B (41% identical), UBE2C (40% identical), CDC34 (38% identical), UBE2R2 (38% identical), UBE2J1 (37% identical), UBE2S (36% identical), UBE2Z (35% identical), UBE2G1 (34% identical), and 12 more.
Diseases named in the same sentence as UBE2N in open-access papers:
UBE2N is named in the same sentence as 78 diseases in open-access papers, as found by Europe PMC text mining. Sharing a sentence is not in itself a finding about the gene and the disease. The quoted sentences say what the papers report.
breast carcinoma (26 papers, 2011 to 2025). "UBE2N is associated with several cancer types including neuroblastoma, breast cancer and B cell lymphoma." (PMID 37161535, 2023). "Loss of UBE2N/Ubc13 inhibited breast cancer cell proliferation, migration, and invasion, presumably increasing dormancy." (PMID 29299114, 2017). "Since breast cancer metastasis is directly associated with the motility of the cells, the effect of UBE2N/Ubc13 silencing on wound healing and migration was investigated." (PMID 29299114, 2017). "Utilizing the same datasets, the gene expression of UBE2N/Ubc13 was found to be significantly increased in high-risk (early disease-related death) breast cancer patients, which correlated with a lower expression of miR-205 and a higher expression of UBE2N/Ubc13 mRNA expression." (PMID 29299114, 2017). "Additionally, meta-analysis of UBE2N/Ubc13 gene expression demonstrated an association between high risk breast cancer phenotype." (PMID 29299114, 2017). "In breast cancer, miR-101 induced mild DNA damage and senescence by targeting UBE2N and SMARCA4, while severe damage reduced miR-101 expression and increased apoptosis." (PMID 40074445, 2025). "UBE2N is a K63-Ub-specific E2 enzyme that has been investigated for its role as a growth promoter of several human cancers such as breast cancer and neuroblastoma." (PMID 37573441, 2023). "Another research demonstrated that UBE2N was highly expressed in primary and metastatic breast cancer, and promoted the metastatic spread of breast cancer cells by controlling their lung-colonizing ability." (PMID 36964266, 2023). "UBE2N is upregulated in various tumor tissues, including breast cancer, neuroblastoma, B-cell lymphoma, colon cancer, and melanoma." (PMID 34199813, 2021). "UBE2N is related to NF-κB signaling and is required for the development of breast cancer metastasis." (PMID 32397371, 2020). "Further, Ubiquitin Conjugating Enzyme E2 N (UBE2N/Ubc13) - metastasis-regulating gene, is a target of these miRNAs and silencing of UBE2N/Ubc13 expression significantly suppressed migration, invasion, and proliferation of breast cancer cells." (PMID 29299114, 2017). "In this work, authors propose that MSC EVs induced dormancy through a mechanism dependent on miRs-205 and 31, suppressing the expression of the UBE2N/Ubc13 gene that is correlated with reduced proliferation, and suppressed migration and invasion of breast cancer cells in vitro." (PMID 33738282, 2021). "Depletion of UBE2N resulted in the suppression of breast cancer metastasis to the lung." (PMID 34199813, 2021). "Additionally, CRISPR sgRNA targeting of UBE2N in breast cancer cell line MDA-MB-231, using three different sgRNAs, revealed similar sensitivities to CX-5461 and PDS." (PMID 33963218, 2021). "Similar to our hypothesis, reports have shown UBE2N is essential for breast cancer metastasis to the lungs in vivo through TGF-β mediated activation of Tak 1 and p38." (PMID 32322560, 2020). "MiR-205 and miR-31 specifically blocked the metastatic ability of breast cancer cells by modulating Ubiquitin Conjugating Enzyme E2 N (UBE2N/Ubc13), which is a common target gene for these miRNAs and is known to be involved in breast cancer metastasis." (PMID 29299114, 2017). "UBE2N interacts with BRCA1, and its expression serves as a potential biomarker of response to poly(ADP-ribose) polymerase (PARP) inhibitors and other DNA-repair-targeted therapies in breast cancer." (PMID 37869102, 2023). "To summarize, hMSC-EVs support primary breast tumor progression but suppress the metastasis of breast cancer cells that are not organ-committed through the UBE2N/Ubc13 pathway and play a role in premetastic niche formation." (PMID 29299114, 2017). "Next, qRT-PCR to analyze the endogenous mRNA levels of UBE2N/Ubc13 with and without treatment with EVs in all the breast cancer cell lines was performed." (PMID 29299114, 2017).
ovarian carcinoma (11 papers, 2015 to 2025). A malignant neoplasm originating from the surface ovarian epithelium. "Reportedly, elevated expression of UBE2N was observed in several cancer types, such as prostate cancer, liver cancer, ovarian cancer, and colorectal cancer." (PMID 40861472, 2025). "Recent studies have characterized UBE2N as a crucial growth promoter of some human tumors, such as ovarian cancer and acute myeloid leukemia, which indicates that UBE2N is an oncogene and potential therapeutic target for cancers." (PMID 38715121, 2024). "LncRNA UCA1 reduced cisplatin response of OAW42 ovarian cancer cells via direct sponging to miR-27a-5p and decreasing the expression of UBE2N levels, resulting in the inhibition of BIM expression, a member of the Bcl-2 family to induce apoptotic death." (PMID 36105363, 2022). "This suggests that UBE2N inhibition constitutes a relevant strategy to sensitize ovarian cancer cells to cisplatin." (PMID 34160887, 2021). "More importantly, our work in patient‐derived organoids enlightens UBE2N as a highly promising target, paving the way to a new potential therapeutic strategy for the treatment of ovarian cancer." (PMID 34160887, 2021). "The gene UBE2N was found to be key in regulating paclitaxel resistance in ovarian cancer cells." (PMID 40643517, 2025). "UCA1 accelerated cisplatin resistance via miR-27a-5p/UBE2N/BIM axis in ovarian cancer cells." (PMID 36105363, 2022). "Altogether these data suggest that UBE2N inhibition could constitute an interesting therapeutic strategy to sensitize ovarian cancer patients to platinum‐based chemotherapy." (PMID 34160887, 2021). "Interestingly, we have shown that UBE2N inhibition efficiently sensitizes to platinum salt patient‐derived organoid of ovarian cancer." (PMID 34160887, 2021). "It has also been suggested recently in a study in ovarian cancer cells that a decrease in UBE2N expression could promote resistance to Paclitaxel." (PMID 34160887, 2021). "Recent studies demonstrate the involvement of UBE2N in progressive cases of melanoma, HCC, breast, prostate, lymphoma, and ovarian cancer." (PMID 32322560, 2020). "In addition, NF‐kB activation upregulates PDL1, a negative regulator of immune response to tumor cells, and UBE2N inhibition might then help elicit immune‐mediated antitumor response in vivo, or sensitize to anti‐PDL1 therapies currently studied in ovarian cancer." (PMID 34160887, 2021).
melanoma (10 papers, 2020 to 2025). A malignant, usually aggressive tumor composed of atypical, neoplastic melanocytes. "Similarly, in another melanoma cohort, low UBE2N levels were associated with complete response (CR) or partial response (PR) of clinical treatment." (PMID 40861472, 2025). "In the NSCLC and melanoma cohorts, patients in the immunotherapy-responsive group exhibited lower tumoral UBE2N expression." (PMID 40861472, 2025). "UBE2N has been proposed as a promising target in melanoma xenografts and large B‐cell lymphoma cells." (PMID 34160887, 2021). "Blocking the expression of UBE2N and its partners significantly decreased melanoma cell proliferation in vitro and tumor growth in vivo." (PMID 34199813, 2021). "Of note, the study revealed the feasibility of applying a small-molecule inhibitor of UBE2N to suppress melanoma xenograft growth in mice." (PMID 34199813, 2021). "Another study has reported that UBE2N promotes melanoma growth via MEK/FRA1/SOX10 signaling hence proving the role of UBE2N as a potential biomarker for PCa." (PMID 32322560, 2020). "Additionally, researchers have confirmed UBE2N as a potential prognostic indicator, with its expression profile correlating significantly with clinical outcomes and therapeutic responses in melanoma, breast carcinoma, and neuroblastoma." (PMID 40861472, 2025). "In addition to its role in melanoma progression, the authors showed that UBE2N positively regulated and maintained the MEK/FRA1 (Fos-Related Antigen 1)/SOX10 (SRY-related HMG box-containing factor 10) signaling cascade that plays a key role in melanomas." (PMID 33800394, 2021). "UBE2N knockdown resulted in the increased expression of epithelial markers, including E-cadherin, p16, and MC1R, and decreased expression of melanoma malignancy markers, such as SOX10, nestin, and ABCB5." (PMID 34199813, 2021). "The study also identified FRA1 as a key molecule acting downstream of UBE2N to maintain the activity of the MEK/FRA1/SOX10 signaling cascade and promote the malignancy of melanoma." (PMID 34199813, 2021). "It has also been demonstrated that UBE2N and its partners, UBE2V1 and UBE2V2, are required for melanoma cell proliferation, survival, and malignant progression." (PMID 34199813, 2021). "The systemic inhibition of UBE2N by a selective small molecule, NSC697923, impaired melanoma xenograft growth." (PMID 33800394, 2021).
colorectal cancer (9 papers, 2018 to 2025). A primary or metastatic malignant neoplasm that affects the colon or rectum. "On that basis, UBE2N was identified, validated and discussed as a factor that maintains genomic stability and plays an important role in colorectal cancer development in close relation to β-catenin, APC and Wnt signaling." (PMID 31319803, 2019).
viral infection (9 papers, 2010 to 2025). "Disruption of both Ube2D3 and Ube2N expression abrogated the IFN induction following virus infection." (PMID 28469175, 2017). "Here we identify two ubiquitin enzymes Ube2D3 and Ube2N through chromatographic purification as activators for RIG-I on virus infection." (PMID 28469175, 2017). "While the UBE2N-Uev1 interaction is required for the cellular response to both bacterial and viral infections, UBE2N and Mms2 redistribute to the nucleus upon DNA damage and lead to assemblies of complexes within the RAD6 pathway of DNA repair, thus preventing genomic instability and cancer." (PMID 31319803, 2019). "We noticed that on viral infection, Ube2D1/2/4−/− and Ube2N/E1−/− cells produced more IFN than Ube2N−/− cells, which could be due to the negative effect of those E2s on IFN-β." (PMID 28469175, 2017). "Consistently, when Ube2N was knocked down, IFN production in response to viral infection was severely crippled in other mouse primary cells, such as peritoneal macrophage (PEM) and bone marrow-derived macrophage (BMDM)." (PMID 28469175, 2017). "Surprisingly, sh-Ube2N alone severely suppressed IFN (α and β) induction in response to virus infection, while sh-Ube2Ds decreased IFN induction slightly." (PMID 28469175, 2017). "As expected, Ube2D3 was not able to rescue the defect of IFN induction by viral infection in sh-Ube2N-treated cells." (PMID 28469175, 2017). "Remarkably, when Ube2Ds or Ube2N was ectopically expressed in si-Ube2D3/Ube2N−/− cells, MAVS aggregation could be fully restored on virus infection, and IFN induction was also rescued." (PMID 28469175, 2017). "Consistently, MAVS could not form aggregates on virus infection in the absence of both Ube2D3 and Ube2N." (PMID 28469175, 2017). "Indeed, MAVS could not form prion-like aggregates under sh-Ube2N treatment in response to virus infection." (PMID 28469175, 2017). "UBE2N is a ubiquitin enzyme that eases the production of non-embedded polyubiquitin chains and serves as an activator for RIG-I on virus infection." (PMID 37869102, 2023). "Consistently, P5 fraction isolated from sh-Ube2N-treated MEFs showed no activity in stimulating IRF3 dimerization, suggesting that MAVS was not activated on virus infection." (PMID 28469175, 2017).
acute myeloid leukemia (5 papers, 2023 to 2025). Acute myeloid leukemia (AML) is a group of neoplasms arising from precursor cells committed to the myeloid cell-line differentiation. "Gene expression analysis in human acute myeloid leukemia, implicated UBE2N as necessary for maintaining oncogenic immune signaling states." (PMID 37573441, 2023). "In a screen for E2 dependencies in acute myeloid leukemia (AML), ubiquitin conjugating enzyme E2 N (UBE2N) emerged as the top candidate." (PMID 40371639, 2025).
diffuse large B-cell lymphoma (4 papers, 2014 to 2023). "NSC697923 blocks ubiquitin transthioesterification by binding the active site cysteine residue of UBE2N (Ubc13), downregulating constitutive NFκB signaling in primary diffuse large B-cell lymphoma cells." (PMID 33324551, 2020). "And according to a study that the specific inhibitor of E2-conjugating enzyme Ubc13-Uev1A could impede the progression of diffuse large B-cell lymphoma, further research on UBE2N inhibitors could provide an effective method to inhibit the progression of LUAD." (PMID 36964266, 2023).
neuroblastoma (4 papers, 2016 to 2023). Neuroblastoma (NB) is the most common solid, extracranial childhood tumor. "Notably, specific inhibition of UBE2N by a small-molecule inhibitor could induce neuroblastoma cell death, highlighting a potential role for UBE2N as a therapeutic target in cancer therapy." (PMID 36964266, 2023).